SRC (SRC proto-oncogene, non-receptor tyrosine kinase)
Diseases named in the same sentence as SRC in open-access papers (continued):
Sharing a sentence is not in itself a finding about the gene and the disease.
cancer (continued). "The third hub protein is SRC, which is highly expressed in a variety of cancers and activates the JAK/STAT pathway." (PMID 40647128, 2025). "We then explored the methylation levels (beta-values, HumanMethylation450) of MAP1LC3A, OPTN, PINK1, PRKN, SRC, BNIP3L, and BECN1 in pan-cancer and their association with gene expression and the immune cell infiltrates." (PMID 39859167, 2025). "Our study supports these findings, showing upregulated SRC expression across various tumor types, indicating its role in cancer proliferation." (PMID 39859167, 2025). "These mechanistic findings align with the broader pharmacological roles of SRC in inflammation and cancer." (PMID 41465425, 2025). "Crosstalk and compensatory signaling between the RAS/RAF/MEK and FAK/SRC signaling axes have been reported in multiple cancer cell lines and preclinical tumor models." (PMID 40430842, 2025). "Background/Objective: Oncogenic tyrosine kinases (TKs) such as ALK and SRC promote cancer progression, but their effects on metabolic enzymes are still not well understood." (PMID 41154443, 2025). "We describe that BAP1 loss increases the mRNA expression and activation of the proto-oncogene SRC in several cancers, suggesting that BAP1 is a transcriptional repressor of SRC." (PMID 40754831, 2025). "We now provide a rationale for stratifying patients with BAP1-mutant cancers for treatment with SRC inhibitors and autophagy inducers." (PMID 40754831, 2025). "These proteins are involved in critical cancer-related pathways, including SRC in the MAPK signaling pathway, ABL1 in JAK/STAT signaling, PIK3CA in the PIK3-Akt pathway, and MAPK3 in the Ras signaling pathway." (PMID 40105884, 2025). "Network-based interactome analysis identified PIK3R1, SRC, and ESR1 as highly connected nodes within cancer-associated signaling networks." (PMID 40649280, 2025). "In our initial experiment, we examined the effectiveness of simultaneously inhibiting both AXL and SRC in various cancer cell lines." (PMID 39941857, 2025). "ASPH is upregulated in various cancer types, where it promotes cancer progression mainly by regulating the Notch1 and SRC pathways." (PMID 38817852, 2024). "Our original results showed that silencing EphA2 was associated with reduced activation of ERK1/2, SRC, and AKT, which are key pathways involved in cancer cell survival and proliferation." (PMID 39056783, 2024). "Further, SRC activity has been implicated in many types of cancers, implicating the reduction of the NADH/NAD+ ratio in cancers." (PMID 38789545, 2024). "It was reported that SRC phosphorylates CDK1 at Tyr15 and then cause mitotic slippage, leading to resistance of cancer cells to microtubule‐targeting agents." (PMID 37842807, 2024). "HNF1A specifically activates the transcription of the proto-oncogene SRC from an alternative promoter, giving rise to the long isoform c-SRC, whose transcripts are differentially present in several cancers, depending on the level of HNF1A." (PMID 38893242, 2024). "SRC has been demonstrated to have significant synergies with the AR, which offers a strong driving force for malignant tumor progression." (PMID 39771106, 2024). "Previous studies have shown that SRPX2 promoted cancer progression via activating FAK/SRC/ERK pathway." (PMID 39333496, 2024). "Studies were also reported that α6β4 integrin mediated SRC/β-catenin signaling enhances cancer stemness properties by upregulating CD44 and EGFR47." (PMID 38839865, 2024). "By acting as a regulatory “pin” molecule, CBL can exert control over the activity and expression of SRC, thereby influencing the downstream signaling pathways involved in cancer progression, including the PI3K/AKT pathway." (PMID 39130630, 2024).
cancer (continued). "Dasatinib is an inhibitor of SRC family kinases; targeting inhibition of SRC with dasatinib has been well-applied in various cancers." (PMID 36672292, 2023). "SRC activation induced, while inhibition of SRC kinase reduced the cancer stemness, tumor cell growth and metastasis in vitro and in vivo." (PMID 36633714, 2023). "Phosphorylation at tyrosine 10 by upstream kinases, HER2 and SRC has been reported to induce activation of LDHA promoting cancer cell invasion, anoikis resistance, and tumor metastasis." (PMID 37507768, 2023). "Disruption of YAP1-KLF5 module in TNBC cells dramatically attenuated the SRC-induced cancer stemness and metastasis in vitro and in vivo." (PMID 36633714, 2023). "SFKs, including SRC, are frequently activated in many types of cancers and promote cancer progression." (PMID 37443730, 2023). "As a result, the expression of these genes, including the proto-oncogene SRC, is modulated and a SRC reduction promotes growth arrest in human cancer cells by inducing DNA damage." (PMID 37679807, 2023). "The bioinformatic analysis confirmed that JAK2 and SRC mRNA levels were up-regulated in a variety of cancers." (PMID 37147297, 2023). "The results showed that apart from EPAS1 and RAD51AP1 that without immunohistochemistry data, SQLE, CAPG, RRM2, SLC1A5, and SRC as dangerous genes were higher expressed in cancer tissues." (PMID 37461802, 2023). "Yet to our knowledge, no study has been conducted to investigate the interaction between THY1 and SRC in NPC cancer development or the functional relevance of their interaction." (PMID 37046850, 2023). "Taken together, our results demonstrated that SRC-GOF enhanced cancer stemness, tumor cell growth and metastasis in TNBCs." (PMID 36633714, 2023). "Here, we identified YAP1 as the key downstream substrate of SRC-induced cancer stemness and metastasis in TNBC cells." (PMID 36633714, 2023). "Overall, these results suggest that TGF-β-induced SRC upregulation promotes cancer cell invasion and metastasis in a subset of human malignancies." (PMID 37439249, 2023). "TGF-β-induced SRC upregulation then promotes cancer cell invasion and metastasis in a subset of human malignancies." (PMID 37439249, 2023). "JAK2 and SRC overexpression or overactivation are closely related to the development, maintenance and progression of cancers, suggesting that JAK2 and SRC are effective targets for cancer therapy." (PMID 37147297, 2023). "Taken together, all our results suggested that SRC regulated the cancer stemness, tumor cell growth and metastasis in TNBC cells." (PMID 36633714, 2023). "A number of SRC-like inhibitors are currently used in the clinics, such as dasatinib or bosutinib, as SRC is an important promoter of cancer exosomes." (PMID 37689664, 2023). "Despite decades of work on SRC, its contribution as a regulator of cancer-related inflammation has remained largely unexplored." (PMID 36759733, 2023). "Altogether, our work presents a novel tyrosine phosphorylation-dependent YAP1-KLF5 oncogenic module governing SRC-induced cancer stemness and metastasis in TNBC." (PMID 36633714, 2023). "For example, phosphorylation of YAP1 by the YES is necessary for survival and tumorigenesis β-catenin-driven cancers, which are sensitive to the SRC inhibitor Dasatinib." (PMID 36633714, 2023). "In our study, we have also identified KLF5 as a YAP1 tyrosine phosphorylation-dependent interacting transcriptional factor to mediate SRC activation-enhanced cancer stemness and metastasis in TNBCs." (PMID 36633714, 2023). "As SRC is a key protein in tumour progression, various small-molecule inhibitors of SRC have been developed for anti-cancer therapy." (PMID 37439249, 2023). "SRC is known to influence adhesion stabilization on carcinoma cells to ECM and is also reported to impact corneal wound healing." (PMID 37189443, 2023).
cancer (continued). "When DDR2 binds to extracellular collagen, it triggers SHP-2, SRC, and mitogen-activated protein kinase signaling; hence, DDR2 mutations induce cancer cell proliferation, differentiation, and metastasis." (PMID 36499051, 2022). "A previous study showed that increased SRC expression and activity promoted cancer progression processes, including cell proliferation, differentiation, invasion and migration." (PMID 35452485, 2022). "Stable knockdown of PTK6 in multiple cancer cell lines leads to decreased activating phosphorylation of SRC." (PMID 36228719, 2022). "Other regulators such as FOXK1, MUC1, PGC-1α, SRC are reported to be involved in miR-485-5p-mediated inhibition of cancer cell proliferation, migration and invasion." (PMID 35706019, 2022). "In agreement with previous reports that indicate the importance of pSTAT3 and pSRC in PDAC, IHC-IF staining showed both elevated activated STAT3 and SRC in tumor cells of human PDAC cancer tissues." (PMID 36324587, 2022). "FAK and SRC are kinases that promote cancer growth and progression, which play a role in activating downstream cellular signaling pathways required for the survival, proliferation, adhesion, and invasion of cells." (PMID 35566311, 2022). "In all experimental results, cancer cells expressing c-MET/ICAM-1/SRC together showed the highest malignancy, and p-SRC activity was also upregulated." (PMID 35487888, 2022). "c-MET has been reported to be associated with most human cancers, which can stimulate various downstream signaling pathways in tumor cells, such as PI3K/AKT, Wnt/β-catenin, JAK/STAT, Ras/MAPK, and SRC." (PMID 35236826, 2022). "These 50 drugs were also found to be validated in different cancer cell lines, such as dasatinib, captopril, leflunomide, and dextromethorphan targeting SRC, MMP2, PTK2B, and RAC1 hub genes, respectively." (PMID 35456223, 2022). "As a tyrosine kinase, SRC carries out its cancer-promoting functions mainly through catalyzing the tyrosine phosphorylation of various protein substrates." (PMID 36581908, 2022). "The expression levels of EGFR, HSP90AA1, and SRC at the transcriptional level of RC were significantly different between normal and cancer tissues (all p < 0.05)." (PMID 36569844, 2022). "Among these SRC-associated RTKs, EGFR overexpression has been observed in a variety of cancer types, including BC." (PMID 36581908, 2022). "At the transcriptional level of CC, EGFR, HSP90AA1, and SRC expression levels were significantly different between normal and cancer tissues (all p < 0.05)." (PMID 36569844, 2022). "Previously, ITGBL1 was reported to promote metastasis in various types of cancers by controlling either Wnt-PCP signaling or the FAK/SRC or TGF-β signaling pathways." (PMID 35066808, 2022). "As the oldest oncogene, SRC was one of the best-studied targets for cancer therapy, which was closely related to regulating appreciation, angiogenesis, invasion metastasis, and bone metabolism." (PMID 36466554, 2022). "Here, we have shown that despite either inherent or drug‐induced resistance to MEK inhibitors, inhibition of SRC using AZD0424 can effectively block cancer cell invasion in vitro." (PMID 34856074, 2022). "Studies have shown that the activation of SRC proto-oncogene non-receptor tyrosine kinase (SRC) can inhibit cancer cell ferroptosis by inhibiting the expression of acyl-CoA synthetase long-chain family member 4 (ACSL4)." (PMID 35795552, 2022). "In sporadic human cancers, c-SRC activity is typically enhanced based on c-SRC conformational changes induced by partner proteins including members of the CRK-associated substrate (CAS) family proteins." (PMID 35410460, 2022). "SRC was also shown to align to the EGFR molecule to facilitate it’s signaling both upstream and downstream and is linked to stemness of cancer cells." (PMID 36163190, 2022). "SRC activation is widely observed in many types of cancer, such as in solid tumours arising from the colon, breast, lung, liver and pancreas." (PMID 34856074, 2022).
cancer (continued). "The protein kinase SRC is a master regulator of cancer cell proliferation, metastasis and invasion, and it also potentiates cancer processes such as neo-angiogenesis." (PMID 33130216, 2021). "KDR, SH2D2A, SRC, and KRAS were included in the VEGF signaling pathway, of which variants were associated with cancer recurrence when they were assessed simultaneously." (PMID 34599262, 2021). "Treatment with eCF506 resulted in increased antitumor efficacy and tolerability in syngeneic murine cancer models, demonstrating significant therapeutic advantages over existing SRC/ABL inhibitors." (PMID 34417202, 2021). "Then, we found that elevated SRC expression contributed to immunosuppressive microenvironment mediated by immune checkpoint molecules of BCa and other cancers." (PMID 33830879, 2021). "ESR1 Cr values strongly positively correlated with ESR2 Cr only in unchanged tissue and was moderately correlated with both PELP1 Cr and SRC Cr in cancer affected tissue." (PMID 34207568, 2021). "The common TMPRSS2 and FURIN associated genes CTSL, MYC, AKT1, and SRC displayed positive correlations with their corresponding subjects except for the FURIN and MYC correlation in cancers (R 0.012; p 0.199)." (PMID 33796097, 2021). "SRC Cr was moderately and negatively correlated with ESR1/SRC ratios only in tissue affected by cancer." (PMID 34207568, 2021). "In the nucleus of normal and cancer cells, SRC is involved in several activities involving both its enzymatic activity as tyrosine kinase and its capability to interact with other protein thereby forming protein complexes." (PMID 33503805, 2021). "High expression of CD44 promotes SRC activation to induce cancer stemness and EMT features of GBM cells." (PMID 34681583, 2021). "Spearman correlations between SRC and immunoinhibitors and abundance of tumour-infiltrating lymphocytes (TILs) across human cancers were applied." (PMID 33830879, 2021). "Problem 1 asked teams to predict molecules that bound the RETM955T-associated cancer targets RET[M918T], BRAF, SRC, S6K, and avoided binding to MKNK1, TTK, ERK8, PDK1, and PAK3." (PMID 34520464, 2021). "SRC role in the development of many types of cancer is well established so that SRC inhibitors have been developed." (PMID 33915954, 2021). "70% of patients had coamplifications of receptor tyrosine kinase or other cancer-promoting genes, including MET, KRAS, FGFR1, IGFR1, SRC and VEGFA18–20, potentially associated with resistance to EGFR-inhibitors." (PMID 33199443, 2021). "Following this idea, we performed a preliminary analysis in which we correlated LCK and SRC mRNA expression in about 500 human cancer cell lines with the metastatic potential of the respective cells." (PMID 34116687, 2021). "In summary, we describe the discovery of CCT3833, a new panRAF/SRC inhibitor, and show that it is effective in KRAS-mutant cancer models, because RAF and SRC are central nodes in KRAS-mutant cancers." (PMID 33130216, 2021). "The product of the human SRC gene, c-Src, is found to be overexpressed and highly activated in a wide variety of human cancers and plays a key role in progression and metastasis." (PMID 34445479, 2021). "On the other hand, CGI reported SRC as the only predicted cancer driver with an oncogenic function, whereas OGFOD2 and ZNF408 were annotated as passenger mutations." (PMID 33916261, 2021). "The attention on cancer metabolism was definitively taken away by the discoveries of oncogenes and tumour suppressor genes starting from the SRC oncogene initially isolated in Rous sarcoma retrovirus and later in human cells." (PMID 34070384, 2021).
cancer (continued). "SRC plays a crucial role in cancer cell plasticity and has been described as a key player in EMT in solid tumors, via its association with FAK and β‐integrins." (PMID 34532864, 2021). "Next, we tested the clinical relevance of baseline SRC protein and mRNA expression in two independent confirmatory cohorts (TCGA, n = 404; GSE13507, n = 162) and prognostic role of SRC in cancers." (PMID 33830879, 2021). "Initial observations showed that SRC activity was positivetily correlated with cancer progression into a metastatic state." (PMID 34193161, 2021). "Recently, it has been suggested that both HPV and EBV oncoproteins induce the initiation of EMT and the progression of human carcinomas through interactions with the JAK/STAT/SRC, β-catenin, PI3k/Akt/mTOR, and/or RAS/MEK/ERK signaling pathways." (PMID 34399719, 2021). "It has been demonstrated that when integrins carried in cancer EVs were internalized by target cells, they activate SRC phosphorylation and pro-inflammatory S100 gene expression." (PMID 33050649, 2020). "Previous studies have shown that ETS-1 is a crucial SRC effector protein that regulates cancer cell proliferation, anti-apoptosis, and metastasis." (PMID 32435511, 2020). "In complex with HSP70, BAG3 has already been shown to interact with the SH3 domain of SRC via its PxxP region, thus affecting SRC signaling pathway in cancer cells." (PMID 33158300, 2020). "Thousands of direct gene targets of this drug are verified (these genes are significantly enriched in cancer such as SRC and HRAS)." (PMID 32328408, 2020). "It was reported that overexpression of LOXL2 drove EMT via upregulating the expression of SNAIL (SNAI1/2), ZEB (ZEB1/2) via IRE1-XBP1 signaling pathway or FAK/SRC signaling pathway in cancer cells." (PMID 32211324, 2020). "Consistent with their ubiquitous expression and their role in different cancer types, SRC, FYN, and YES were found hyperactive and highly expressed in MM cells, suggesting their involvement in MM malignancy." (PMID 32664483, 2020). "Noteworthily, it has been demonstrated that SRC can affect glycolysis in cancer cells through a direct phosphorylation of pyruvate dehydrogenase (PDH), inhibiting its activity and driving the Warburg effect." (PMID 32545574, 2020). "RARA, SRC and SMO can also potentially be used as diagnostic, prognostic and/or therapy-response biomarkers in cancer." (PMID 32099096, 2020). "Since the discovery of SRC as a proto-oncogene, the role of SRC in cancers has been largely investigated, and due to the rare cases of gene mutation and amplification, it has remained unclear for a long time." (PMID 33020459, 2020). "Then, much evidence supported the oncogenic role of SRC mainly due to the interaction with various signaling molecules activating pathways for the promotion, maintenance, and progression of several cancers." (PMID 33020459, 2020). "The product of the human SRC gene, c-Src, is overexpressed and often activated in many human cancers." (PMID 32070055, 2020). "The crosstalk between integrins, growth factor receptors and SRC oncogene is readily exploited by cancer cells during both tumour initiation and disease progression." (PMID 31330086, 2019). "This suggests that integrins are one important driver of SRC-mediated YAP/TAZ activity in cancer cells." (PMID 30559289, 2019). "Elevated SRC expression and activity has been frequently detected in multiple cancers, including breast, ovarian, colon, pancreatic, gastric, hepatocellular, lung, bladder esophageal, and HNSCC." (PMID 31731442, 2019). "This makes SRC, and the pathways that activate it, potential therapeutic targets in cancers that are dependent upon YAP and TAZ." (PMID 30559289, 2019). "Aberrant SRC expression and activation is frequently detected in multiple cancers, and hence, targeting SRC has emerged as a promising therapeutic strategy." (PMID 31731442, 2019).